SLC7A1 (solute carrier family 7 member 1)
Diseases named in the same sentence as SLC7A1 in open-access papers (continued):
Sharing a sentence is not in itself a finding about the gene and the disease.
meningioma (continued). "Based on the drug sensitivity data from the GDSC database, we predicted the potential drugs targeting SLC7A1 expression in meningioma." (PMID 41184266, 2025). "The results revealed a significant reduction of FOXM1 and E2F4 upon SLC7A1 knockdown in meningioma cells." (PMID 41184266, 2025). "By analyzing the bulk transcriptomics data of three meningioma datasets, we found that SLC7A1 expression was significantly upregulated in high-grade meningioma." (PMID 41184266, 2025). "GDSC analysis combined with experimental validation showed that AZ628 was a potential antitumor drug for high-SLC7A1 meningioma." (PMID 41184266, 2025). "All these results confirmed that high SLC7A1 expression contributed to malignant phenotypes of meningioma." (PMID 41184266, 2025). "Interestingly, GSVA analysis at the single-cell level also revealed a significant increase in the transcriptional activity scores of FOXM1 and E2F4 in clusters 4 and 9 of meningioma cells with high SLC7A1 expression." (PMID 41184266, 2025). "In addition, the bulk-level GSEA analysis also demonstrated a significant upregulation of transcriptional activity for FOXM1 and E2F4 in meningioma samples from the high-SLC7A1 group compared to the low-SLC7A1 group." (PMID 41184266, 2025). "Additionally, AZ628 treatment also inhibited the transcriptional activity and protein expression of FOXM1 and E2F4, mirroring the effects of SLC7A1 knockdown in meningioma." (PMID 41184266, 2025). "Furthermore, we conducted a comprehensive analysis of the role of SLC7A1 in meningioma at both the single-cell and bulk levels." (PMID 41184266, 2025). "We found 17 drugs with lower IC50 in the high-SLC7A1 group, indicating that they might have better antitumor effects on meningiomas with high expression of SLC7A1." (PMID 41184266, 2025). "Consistently, similar results were obtained from RNA sequencing analysis after knocking down SLC7A1 in meningioma cells, further suggesting the potential oncogenic role of SLC7A1 in meningioma through the regulation of E2F targets, G2M checkpoint, and MYC targets pathways." (PMID 41184266, 2025). "Overexpression of SLC7A1 in meningioma cells may also create an arginine-depleted microenvironment by enhancing arginine uptake into tumor cells." (PMID 41184266, 2025). "However, further research is needed to elucidate the molecular mechanisms underlying the regulation of transcription factors FOXM1 and E2F4 by SLC7A1 in meningioma." (PMID 41184266, 2025). "Transwell assay showed that SLC7A1 knockdown also suppressed the invasion of meningioma cells." (PMID 41184266, 2025). "Considering the vital role of SLC7A1 in meningioma, targeting SLC7A1 may be a valuable strategy to treat meningioma." (PMID 41184266, 2025). "We predicted the potential drugs targeting SLC7A1 expression in meningioma." (PMID 41184266, 2025). "Furthermore, AZ628 treatment also inhibited the expression of SLC7A1 in meningioma cells, indicating that AZ628 is a potential anti-meningioma drug that targets SLC7A1." (PMID 41184266, 2025). "Furthermore, the differential expression of SLC7A1 between high-grade meningioma and grade 1 meningioma has also been validated at the protein level by IHC." (PMID 41184266, 2025). "Moreover, we performed virtual knockdown analysis using the RNA sequencing data from the GSE136661 dataset to infer the functional role of SLC7A1 in meningioma at the bulk level." (PMID 41184266, 2025). "Additionally, SLC7A1 may exert oncogenic functions in meningioma by regulating transcription factors FOXM1 and E2F4." (PMID 41184266, 2025). "Therefore, SLC7A1 may facilitate the malignant progression of meningioma through the regulation of E2F targets, G2M checkpoint, and MYC targets pathways via the SLC7A1-FOXM1/E2F4 axis." (PMID 41184266, 2025). "Expression analysis revealed higher SLC7A1 expression in IOMM-Lee and SZ8511 compared to SZ2614, further indicating the targeted inhibitory effect of AZ628 on meningiomas with high SLC7A1 expression." (PMID 41184266, 2025).
meningioma (continued). "Single-cell analysis revealed that SLC7A1 and SLC7A2 are expressed in meningioma cells, exhibiting mutual exclusivity in expression, while SLC7A3 is barely expressed." (PMID 41184266, 2025). "Moreover, we demonstrated that SLC7A1 regulates multiple signaling pathways involved in tumor proliferation, including E2F targets, G2M checkpoint, and MYC targets, in meningioma." (PMID 41184266, 2025).
non-small cell lung carcinoma (2 papers, 2024). A group of at least three distinct histological types of lung cancer, including non-small cell squamous cell carcinoma, adenocarcinoma, and large cell carcinoma. "In non-small cell lung cancer with KRAS mutations, the expression of arginine succinate synthetase is silenced, leading to a dependence on the arginine transporter SLC7A1 for arginine uptake from the extracellular environment." (PMID 39744129, 2024). "SLC7A1-mediated arginine uptake as a potential therapeutic vulnerability in non-small cell lung cancer." (PMID 38903179, 2024). "Thus, SLC7A1-mediated arginine uptake becomes a potential therapeutic vulnerability for the treatment of KRAS-mutant non-small cell lung cancer." (PMID 39744129, 2024).
serous ovarian cancer (2 papers, 2022 to 2024). "Further exploring the signaling pathways in tumors, ssGSEA analysis showed that while SLC7A1 was highly expressed in patients with serous ovarian cancer, TGF‐β and EMT pathways were significantly enriched (p < 0.05)." (PMID 38752472, 2024). "Next, the expression of SLC7A1 protein in human high-grade serous ovarian cancer tissues (HGSOC) (n = 20), normal ovarian tissues (N-ovary) (n = 5), and normal fallopian tubes (N-FT) (n = 5) was detected by immunohistochemistry (IHC)." (PMID 36131790, 2022). "In later studies, we found that SLC7A1 is also highly expressed in the interstitial portion of high‐grade serous ovarian cancer (HGSOC), but the significance of this high expression in the interstitial remains unclear." (PMID 38752472, 2024).
Acute Myeloid Leukaemia (1 paper, 2017). "We have shown that SLC7A1 is predominant in both adult and paediatric Acute Myeloid Leukaemia blasts which are dependent on arginine for survival." (PMID 28969007, 2017).
alveolar proteinosis (1 paper, 2017). "We speculate that the lack of SLC7A1 in AMs may increase susceptibility to lysine depletion in this cell type thereby possibly leading to both higher risk of alveolar proteinosis and moderate increase of lysine levels in plasma of patients with poorer outcome." (PMID 28057010, 2017).
anemia (1 paper, 2016). A reduction in the number of red blood cells, the amount of hemoglobin, and/or the volume of packed red blood cells. "One locus also affects two hematological measures and contains a gene (Slc7a1) causing severe anemia in the mouse." (PMID 27233670, 2016).
bladder urothelial carcinoma (1 paper, 2024). "In addition, a group of disulfidptosis-related genes (GYS1, LRPPRC, NDUFA11, OXSM, RPN1, SLC3A2, and SLC7A1) are found to influence the prognosis of bladder urothelial carcinoma via immune cell infiltration." (PMID 39701955, 2024).
cervical cancer (1 paper, 2024). A primary or metastatic malignant neoplasm involving the cervix. "Our research demonstrated that SLC7A1 is highly expressed in the risk model of CC and is associated with prognosis in cervical cancer patients." (PMID 38903179, 2024).
chronic renal failure (1 paper, 2020). "In effects, studies in adult mice have shown that the bilateral ureteral ligation increases glomerular arginine transport via Slc7a1 upregulation, while in chronic renal failure, arginine uptake is attenuated through modulation of Slc7a1." (PMID 32980952, 2020). "Previously, SLC7A1 localization has been reported to the basolateral membrane of the polarized kidney epithelial (MDCK and HEK) cells, while a decrease in its expression was observed during endothelial cell dysfunction related to chronic renal failure." (PMID 32980952, 2020).
developmental delay (1 paper, 2023). "Wang demonstrated that the translational knockdown of SLC7A1 mRNA leads to developmental delay and functional abnormalities in sheep fetuses." (PMID 36835615, 2023).
Duchenne muscular dystrophy (1 paper, 2018). Duchenne muscular dystrophy (DMD) is a neuromuscular disease characterized by rapidly progressive muscle weakness and wasting due to degeneration of skeletal, smooth and cardiac muscle. "The DYS-HAC was transferred to Duchenne muscular dystrophy patient-derived fibroblasts from CHO cells, from which iPSCs were generated using a combination of lentiviral infection for expressing mouse SLC7A1 and retroviral infection for expressing KLF4, SOX2, OCT4, and c-MYC." (PMID 32161806, 2018).
Ewing sarcoma (1 paper, 2017). A small round cell tumor that lacks morphologic, immunohistochemical, and electron microscopic evidence of neuroectodermal differentiation. "For Ewing's sarcoma the expression levels of amino acid transporters are more equally distributed although SLC7A1 was again the most predominant." (PMID 28969007, 2017). "In contrast for Ewing's sarcoma, low ASS expression was associated with poorer overall survival (p=0.0013), and high SLC7A1 expression was associated with poorer overall survival (p=0.019)." (PMID 28969007, 2017).
gastric cancer (1 paper, 2021). A primary or metastatic malignant neoplasm involving the stomach.
leukemia (1 paper, 2016). A malignant (clonal) hematologic disorder, involving hematopoietic stem cells and characterized by the presence of primitive or atypical myeloid or lymphoid cells in the bone marrow and the blood. "Intriguingly, in addition to its role in metabolic L-Arg uptake by numerous cells, constitutive SLC7A1 has been also shown to be the receptor for ectopic murine leukemia viruses." (PMID 27783672, 2016).
lung adenocarcinoma (1 paper, 2023). A carcinoma that arises from the lung and is characterized by the presence of malignant glandular epithelial cells. "It has been reported that increased AHR protein levels inhibit ferroptosis in human lung adenocarcinoma PC-9 cells by increasing the expression of SLC7A1, a molecule that suppresses ferroptosis by reducing the reactive oxygen species content." (PMID 37894798, 2023).
lymph node metastasis (1 paper, 2022). "Their interactions, as immunosuppressive signaling, were strongly associated with the presence of tumor and local lymph node metastasis in T2 and T3 samples, which was confirmed in TCGA cohort, with the high expression of SLC7A1 being significantly associated with lymph node metastasis." (PMID 35515000, 2022).
neuroblastoma (1 paper, 2025). Neuroblastoma (NB) is the most common solid, extracranial childhood tumor. "Expression of SLC7A1/CAT-1, the predominant arginine importer in primary neuroblastoma tumors and in the 4 selected neuroblastoma cell lines, was variably affected by BCT-100 exposure in a cell line- and concentration-dependent manner in vitro." (PMID 40813699, 2025).
osteosarcoma (1 paper, 2017). A usually aggressive malignant bone-forming mesenchymal neoplasm, predominantly affecting adolescents and young adults. "Within osteosarcoma we identified that cells have higher expression of the SLC7A1 and SLC7A2 amino acid transporters, compared to the SLC7A3 and SLC7A4 transporters consistent with the established role of these isoforms in transporting arginine and other key amino acids such as lysine and ornithine." (PMID 28969007, 2017).
rhabdomyosarcoma (1 paper, 2017). A rare aggressive malignant mesenchymal neoplasm arising from skeletal muscle. "In rhabdomyosarcomas SLC7A1 and SLC7A4 were strongly expressed, with low SLC7A2 (SLC7A3 not available)." (PMID 28969007, 2017).
sarcoma (1 paper, 2017). A usually aggressive malignant neoplasm of the soft tissue or bone. "The analysis above indicates that the major paediatric sarcomas universally express SLC7A1, ARG2, and ASS, but have low OTC expression." (PMID 28969007, 2017).
thyroid cancer (1 paper, 2023). "Circ0067934 upregulates SLC7A1 expression via the miR-545-3p/SLC7A11 axis, which inhibits thyroid cancer cell ferroptosis and promotes thyroid cancer growth and metastasis." (PMID 37168995, 2023).
tumor (29 papers, 2010 to 2025). "The EMT process leads to the loss of E‐cadherin in tumor cells and the high expression of N‐cadherin, which is also an important reason for first‐line chemotherapy resistance.SLC7A1 knockdown in tumor cells impaired cellular EMT progression." (PMID 38752472, 2024). "ITGA5 and SLC7A1 were found to be overexpressed in CC tumor tissues and were associated with a worse prognosis, except for LCK, GCH1 and TNFRSF9." (PMID 38903179, 2024). "We found that SLC7A1 was correlated with immune components in the tumor microenvironment and highly enriched in cancer-associated fibroblasts (CAFs) (P = 0.00792)." (PMID 36131790, 2022). "And the positive correlation between ITGA5, NOD2, P2RX4, RIPK2, SLC7A1 and immune score indicated that the tumor tissue in the high-risk group is highly infiltrated by immune cells, which is consistent with risk score." (PMID 33828988, 2021). "In addition, the expression level of SLC7A1 was closely associated with tumor proliferation index and patient prognosis." (PMID 41184266, 2025). "Furthermore, lentiviral-mediated suppression of SLC7A1 was associated with decreased cell proliferation, cell viability, and tumor growth." (PMID 38705513, 2024). "SLC7A1 has been reported to promote tumor cell proliferation by regulating cellular uptake of arginine." (PMID 41184266, 2025). "This metabolic imbalance likely reflects the spatial heterogeneity within the TME, where tumor cells sequester arginine through the transporter SLC7A1, while stromal and immune cells, particularly neutrophils in the LAS subgroup, face arginine depletion." (PMID 41208994, 2025). "Our results revealed that SLC7A1 regulates multiple signaling pathways involved in tumor proliferation, including E2F targets, G2M checkpoint, and MYC targets." (PMID 41184266, 2025). "These pathways exhibited a substantial increase in NES, indicating a strong correlation between SLC7A1 expression and tumor proliferation." (PMID 41184266, 2025). "In this study, the inflammatory response genes (ITGA5, LCK, GCH1, TNFRSF9 and SLC7A1) play different role in immune tumor microenvironment." (PMID 38903179, 2024). "Based on this study, SLC7A1 was expressed in 70.5% of CRC samples, and silencing SLC7A1 using siRNA inhibits tumor cell growth by 20–50%." (PMID 38705513, 2024). "In summary, according to our previous studies, SLC7A1 expression is elevated in both tumor parenchymal cells and CAFs in HSCOC." (PMID 38752472, 2024). "In both tumor cells and CAFs, the high expression of SLC7A1 promotes the malignant progression of tumors, so SLC7A1 is undoubtedly a very important gene in the progression of HGSOC." (PMID 38752472, 2024). "SLC7A1 plays an important role in the uptake of arginine and is involved in the regulation of T cells and tumor cells biological behavior." (PMID 38752472, 2024). "Transwell assay, scratch assay, cck8 assay and cell adhesion assay showed that SLC7A1 highly expressed in CAFs promoted tumor cells invasion, migration and metastasis in vitro." (PMID 38752472, 2024). "In epithelial ovarian cancer, SLC7A1 regulates metabolism reprogramming in promoting tumor progression." (PMID 38705513, 2024). "SLC7A1 overexpression in tumor cells promotes the proliferation, migration, invasion, and platinum resistance of cancer cells, and participates in amino acid metabolism remodeling of cancer cells." (PMID 38752472, 2024). "Researchers believe that the main mechanism underlying this effect is that IFNγ released by CD8+ T cells downregulates the expression of SLC3A2 and SLC7A1 in tumor cells and inhibits the uptake of cystine by tumor cells." (PMID 34975326, 2022). "Another study showed that SLC7A1-mediated arginine transport is involved in T cell proliferation and thus in the process of tumor immune escape." (PMID 36131790, 2022).